HMOX1 (heme oxygenase 1)
Diseases named in the same sentence as HMOX1 in open-access papers (continued):
Sharing a sentence is not in itself a finding about the gene and the disease.
diabetic nephropathy (94 papers, 2011 to 2026). "The association of the HMOX1 GTn length polymorphism with other primary endpoints such as stroke, diabetic kidney disease, peripheral artery disease or severe diabetic retinopathy was neither significant in men nor in women, although there was a trend suggesting that LL carriers had more events." (PMID 40826355, 2025). "In diabetic nephropathy, the mechanism of luteolin's renoprotective property could be associated with increased heme oxygenase 1 (HO-1) expression and antioxidant levels." (PMID 35832521, 2022). "A recent in vivo study showed that β-cryptoxanthin reduces hyperglycemic-induced podocyte injury in diabetic kidney disease by enhancing Nrf2/heme oxygenase-1 signaling pathways." (PMID 40143179, 2025). "SGLT-2 played a renoprotective role in diabetic Kidney disease, at least in part, through alleviating Hypoxia-inducible factor 1 alpha/Heme oxygenase 1-mediated ferroptosis." (PMID 38879701, 2024). "Hmox1 induction helps mitigate oxidative stress-mediated damage and inflammation, contributing to improved kidney function in diabetic kidney disease." (PMID 39064752, 2024). "It was recently revealed that the expression of Nrf2 and downstream molecules, heme oxygenase-1 (HO-1) and GPx, are downregulated in mouse models of diabetic nephropathy and IgA nephropathy." (PMID 37894915, 2023). "Biomarkers of diabetic nephropathy include urinary heme oxygenase-1 (HO-1) and 8-hydroxydeoxyguanosine, and circulating microRNA 130b." (PMID 36769060, 2023). "One study suggested that HIF-1α exerts a protective role in diabetic nephropathy by upregulation heme oxygenase-1 (HO-1) expression to regulate the mitochondrial dynamics." (PMID 36211825, 2022). "Heme oxygenase 1 (HO-1), also named heme oxygenase-1 (HO-1), expression upregulation in high glucose plus oxidized LDL-treated primary peritoneal macrophages from wild-type mice and Nrf2/HO-1 can be a therapeutic target for diabetic nephropathy." (PMID 34899600, 2021). "Studies also revealed that the expressions of Nrf2 and its downstream molecules, heme-oxygenase-1 (HO-1) and glutathione peroxidase (GPx), were declined in mouse models of diabetic nephropathy and IgA nephropathy." (PMID 31023362, 2019). "Mogs can prevent the development of diabetic nephropathy through antioxidant effects associated with inhibition the activation of heme oxygenase-1 (HO-1) and has no toxic effects in normal mice." (PMID 38638866, 2024). "Our results suggested that protection against development of diabetic nephropathy by luteolin treatment involved changes in superoxide dismutase (SOD) activity, the malondialdehyde (MDA) content and expression of Heme Oxygenase-1 (HO-1) protein." (PMID 21584231, 2011). "In addition, Jin and Chen found that in diabetic kidney disease, umbelliferone inhibits ferroptosis by activating the nuclear factor E2-related factor 2 (NRF-2)/heme oxygenase-1 (HO-1) pathway, significantly improving kidney damage and reducing ROS generation." (PMID 39021564, 2024). "It is known that hydralazine may protect diabetic kidney disease (DKD) patients by inhibiting reactive oxygen species (ROS) through inhibiting xanthine oxidase (XO), consequently stimulating Nrf2-mediated heme oxygenase 1 (HO-1)." (PMID 41007838, 2025). "On the other hand, Nrf2 is a protective signal against diabetic nephropathy by promoting the expression of enzymatic and nonenzymatic antioxidants such as glutathione (GSH), heme oxygenase 1 (HO-1), catalase, and superoxide dismutase (SOD)." (PMID 38675166, 2024).
malaria (93 papers, 2010 to 2026). Malaria is a serious and sometimes fatal disease caused by a parasite that commonly infects a certain type of mosquito which feeds on humans. "Previous studies found that shorter GT repeats correlate with lower HMOX1 expression and a higher risk of severe malaria." (PMID 40993672, 2025). "Against that, there has been little previous evidence that SNPs in or near HMOX1 have previously associated with severe malaria." (PMID 36397106, 2022). "The gene HMOX1 (also known as heme-oxygenase 1) encodes for a protein HO-1 that has been shown to be critical for survival in cerebral malaria in mouse models of malaria." (PMID 36397106, 2022). "In humans, polymorphisms in the promoter of Hmox1, associated with higher expression of the enzyme, correlate with a more severe presentation of malaria." (PMID 30200471, 2018). "This study investigated the possible association between HMOX1 polymorphisms and severity of malaria." (PMID 25888733, 2015). "One such enzyme is HO-1 (encoded by the Hmox-1 gene), known for its role in heme detoxification during malaria by the catabolization of free heme into biliverdin, iron and carbon monoxide." (PMID 26385579, 2015). "Polymorphisms in the promoter of the Haem oxygenase-1 (HMOX1) gene encoding HO-1 have been associated with several diseases including severe malaria." (PMID 25888733, 2015). "Sickle hemoglobin was shown to increase expression of heme oxygenase-1, an enzyme that converts the free heme into antioxidant molecules that are protective against oxidative damage caused by severe malaria." (PMID 25166912, 2014). "A few studies have investigated the associations of the HMOX1 gene polymorphisms with malaria susceptibility in humans." (PMID 24693973, 2014). "In conclusion, the present study has identified several polymorphisms in GCLC, GSR and HMOX1 genes that are associated with oxidative stress status in the blood plasma of two-year old children from a malaria endemic region." (PMID 24693973, 2014). "A microsatellite polymorphism (GT)n was found to be associated with HMOX1 expression and development of symptomatic or severe malaria." (PMID 24693973, 2014). "We have shown that subjects with the long form (≥30 GT repeats) of the HMOX1 gene polymorphism have greater susceptibility to developing malaria and higher inflammatory scores than individuals with the short form." (PMID 23316245, 2012). "The results of some studies have shown that the presence of lower (GT)n repeats in HMOX1 gene is associated with a greater chance of developing severe malaria, suggesting that the increased expression of HO-1 is deleterious for human malaria." (PMID 23316245, 2012). "In the present study we characterized in detail the genetic and functional associations between HMOX1 promoter polymorphisms, HO- 1 inducibility, HMOX1 expression and severity of malaria in Gambian children exposed to seasonal malaria." (PMID 22438807, 2012). "In addition, we measured the expression of two genes that are known to have a hepatoprotective effect in the context of iron loading in malaria: Hmox1 (encodes haemoxygenase-1 (HO-1)) and Fth1 (encodes ferritin heavy chain)." (PMID 37812650, 2023). "The relevance of the HMOX1 polymorphism in malaria has been recently reviewed." (PMID 36397106, 2022). "A variable length, short tandem GT(n) repeat (STR) in HMOX1 that may influence gene expression has been associated with outcomes of human malaria in some studies." (PMID 36397106, 2022). "Intriguingly, a recent study showed that a mouse model of malaria with a renal proximal tubule-specific knockout of heme oxygenase-1 (HO-1), a heme detoxifying enzyme, was more susceptible to AKI, further suggesting the involvement of heme-mediated damage in the propagation of AKI in SM." (PMID 33968051, 2021). "Similarly, HMOX1 gene promoter alleles and SNPs associated to higher HO-1 expression correlate with severe malaria in children." (PMID 32692767, 2020).
malaria (continued). "Interestingly, miR-1304-3p has previously been shown to directly target heme oxygenase-1 (HMOX1) encoding the primary heme-degrading enzyme which has been shown to be protective against severe malaria in mice." (PMID 33037226, 2020). "Although these contrasting results could be, at least in part, explained by different etiologic agents, further studies are required in order to dissect the impact of polymorphisms in HMOX-1 in malaria progression and severity." (PMID 32692767, 2020). "Ex vivo observations show reduced ability for neutrophils to generate ROS during malaria, and this reduced function was associated with increased haemolysis and heme oxygenase-1 (HO-1) expression in infected individuals; similar findings have been reported in asymptomatic infection." (PMID 30619354, 2018). "Based on earlier studies, it was hypothesized that certain polymorphisms in the promoter of the HMOX1 gene encoding HO-1 could confer protection against severe malaria." (PMID 25888733, 2015). "HMOX1 has been associated with several diseases, which may have blurred a possible selective force of malaria on HMOX1." (PMID 25888733, 2015). "Although these factors limit the extrapolation of the association results to other populations our findings suggest the novel hypothesis that in African populations the TGFB2 and HMOX1 genetic variation correlate with malaria genetic susceptibility." (PMID 20585394, 2010). "To investigate the functional basis of HMOX1 association to malaria we examined whether the HMOX1 haplotypes associated to the clinical outcomes of malaria were also controlling the level of HMOX1 gene expression among children developing CM." (PMID 20585394, 2010). "Moreover, LXA4-induced heme oxygenase 1 (HO-1), an enzyme associated with tissue protection, in endothelial dysfunction in vivo and in vitro, which are essential to the prevention of severe malaria development." (PMID 32599864, 2020). "Thus in summary, based on the findings of this study together with the fact that previously found associations between malaria and HMOX1 have shown effects in opposing directions suggest that malaria does not seem to be a major selective force on the polymorphisms of the HMOX1 promoter." (PMID 25888733, 2015). "In addition, one HMOX1 haplotype composed of five CM-associated SNPs increased the risk of developing the CM syndrome (Pcorrec. = 0.002) and was under-transmitted to children with uncomplicated malaria (P = 0.036)." (PMID 20585394, 2010). "Using proximity extension assay (PEA), we identified elevated IgG Fc receptor IIb (FCGR2B) and heme oxygenase-1 (HO-1) in malaria-positive pregnancies, while neurturin (NRTN) and IL-20 were downregulated." (PMID 40697816, 2025). "Numerous mechanisms including sickling of infected RBCs, translocation of HbS-specific parasite-growth inhibiting miRNAs, stimulation of heme-oxygenase-1 and lower oxygen states are plausible explanations for HbSS malaria resistance." (PMID 38413594, 2024). "Malaria derived products such as haemozoin (Hz) and heme oxygenase-1 (HO-1) also contribute to neuroinflammation in CM." (PMID 34692564, 2021). "HO-1 also protects mice in other experimental models of malaria, as demonstrated by the high rates of hepatic failure and death of Hmox1-deficient mice infected with P. chabaudi chabaudi compared to the benign outcome of BALB/C controls." (PMID 32692767, 2020). "This is consistent with increased transcription of Hmox1 and Blvra, the genes encoding HO-1 and BVR, in the liver during acute infection, as well as HO-1 activation during malaria." (PMID 33021470, 2020). "Some inflammatory response genes can be associated with malaria, like TNF-α, NOS2, Interferon-alpha/beta receptor alpha chain gene (IFNAR1), heme oxygenase 1 (HMOX1), TLRs, CD36, and CD40LG." (PMID 32599864, 2020).
malaria (continued). "We revisited genetic evidence provided by inflammatory response genes that have been repeatedly associated to malaria, namely TNF, NOS2, IFNAR1, HMOX1, TLRs, CD36, and CD40LG." (PMID 31417551, 2019). "In the studies described here, we observe a correlation between placental hemozoin density and Hmox1 transcript abundance in malaria-exposed conceptuses." (PMID 31862902, 2019). "In malaria, tolerance mechanisms have been ascribed to heme oxygenase-1, carbon monoxide, ferritin and nitric oxide, though these mechanisms are likely to be interlinked." (PMID 30375380, 2018). "In a murine model for malaria, this effect was attributed to the induction of the cytoprotective heme oxygenase 1 in neutrophil progenitors of the bone marrow." (PMID 28804484, 2017). "Numerous studies have reported on associations of the genetic variants in GSR, GCLC, HMOX1 and SOD2 with oxidative stress related disorders and conditions including malaria." (PMID 24693973, 2014). "In contrast, many macrophage inhibition-related genes were up-regulated after malaria, including haem oxygenase 1 (HMOX1), JunB, and IRF1." (PMID 24188121, 2013). "In light of this, it has been hypothesized with regard to the effect of the (GT)n repeat length polymorphism in the HMOX1 gene promoter that – in contrast to what has been observed for chronic inflammatory conditions - short repeat array alleles may cause susceptibility to severe malaria in humans." (PMID 22438807, 2012). "The protective effect of HbSS against malaria has been attributed to heme oxygenase-1 (HO-1), an enzyme whose expression is strongly induced by sickle hemoglobin." (PMID 23259718, 2012). "Using Plasmodium falciparum malaria that can cause a sepsis-like syndrome as an example, we characterize the associations between the (GT)n polymorphism, HO-1 protein levels and HMOX1-mRNA expression with severity of malaria in 307 Gambian children." (PMID 22438807, 2012). "We provide mechanistic evidence that induction of HMOX1 expression in neutrophils potentiates the respiratory burst, and propose this may be part of the causal pathway explaining the association between short (GT)n repeats and increased disease severity in malaria and other critical illnesses." (PMID 22438807, 2012). "Further research mechanistically linking HMOX1 genetic variation, gene expression of HMOX1 and downstream effects on the host–pathogen interaction would be helpful in understanding the role of heme metabolism in severe malaria." (PMID 36397106, 2022). "We found that recruitment of neutrophils and vascular endothelial growth factor (VEGF) is essential to the pathogenesis of malaria-associated ARDS and that the induction of heme oxygenase-1 (HO-1) has a protective effect against the development of ARDS in mice." (PMID 31871954, 2019). "However, a recent meta-analysis based on a large clinical dataset indicated that an increase in the length of the HMOX1 Short Tandem Repeat (STR) is unlikely to be associated with the occurrence of severe malaria." (PMID 40993672, 2025). "Additionally, Na-Ek and Punsawad identified increased expression of 4-hydroxynonenal (4-HNE) and heme oxygenase-1 (HO-1) in the renal tissue of mice, both markers of oxidative damage and related to acute tubular damage in the kidneys during experimental malaria." (PMID 35682626, 2022). "This study is suggestive that HMOX1 STR variation may not affect the risk of severe malaria, but it remains uncertain whether there may be a suggestive effect, only present under certain environmental conditions." (PMID 36397106, 2022). "Several studies have investigated a possible association between HO-1 and Plasmodium falciparum infections and have demonstrated both increased expression of HO-1 during malaria infection and associations between HMOX1 promoter polymorphisms and malaria disease severity." (PMID 25888733, 2015).
malaria (continued). "In addition, plasma levels of heme, heme oxygenase-1 (HO-1) and CXCL10 were significantly increased compared with non-malaria subjects." (PMID 26555697, 2015). "This was also the case for Hp−/−Hpx−/−Hmox1+/− mice, lacking one Hmox1 allele, suggesting that the extent of renal iron overload imposed by HP and HPX depletion is not sufficient to precipitate the pathogenesis of malaria AKI in adult mice." (PMID 38307624, 2024). "Moreover, the two genes immediately flanking the HMOX1 gene (TOM1 33 kb 5′ and MCM5 6 kb 3′ of HMOX1) are not obvious candidates for malaria susceptibility." (PMID 22438807, 2012).
injury (91 papers, 2011 to 2026). Damage inflicted on the body as the direct or indirect result of an external force, with or without disruption of structural continuity. "As one of the miR-183-5p targets is heme oxygenase-1 (HO-1) (a molecule reported to exacerbate ICH brain injury), the authors investigated the association between agomir-183-5p and antagomir-183-5p injections, HO-1 levels, and cerebral injury." (PMID 41009624, 2025). "In LPS-induced acute lung injury, UA upregulates the Keap1-Nrf2/heme oxygenase 1 (HO-1) pathway to inhibit ferroptosis and reduce lipid peroxide accumulation in lung tissue." (PMID 40722629, 2025). "In endotoxemia-induced acute lung injury, GOLPH3 is highly increased and associated with oxidative stress, inflammation, and apoptosis; which were alleviated by activation of heme oxygenase-1 through reduction of Golgi fragmentation and GOLPH3 expression." (PMID 37479687, 2023). "Heme oxygenase is the initial and rate-limiting enzyme of heme catabolism, and the expression of heme oxygenase-1 (HO-1) is rapidly induced following acute brain injury." (PMID 30177908, 2018). "Also, it is noted that the Kelch-like ECH-associated protein 1 (Keap1)/erythroid 2-related factor 2 (Nrf2)/heme oxygenase-1 (HO-1) is a crucial pathway axis in defense against paracetamol-induced liver injury." (PMID 40569949, 2025). "Modulation of HMOX-1 emerges as a potential therapeutic strategy for HS-related liver injury." (PMID 39309491, 2024). "Moreover, the results of the study indicated that PamHRchol/GA micelles carrying the heme oxygenase-1 (HO-1) gene provide a useful anti-inflammatory therapy for acute lung injury." (PMID 37631235, 2023). "The HIF-1 α /HMOX1 pathway has been verified to be necessary in preventing lung damage; and researchers have discovered that activating the HIF-1/HMOX1 signalling pathway can improve LPS-induced acute lung injury by boosting survival rate, reducing inflammation, and reducing oxidative stress." (PMID 36452079, 2022). "Evidence showed that MA prevented the releases of proinflammatory cytokines by repressing the activation of MAPK and NF-κB signaling pathway and enhancing the expression of heme oxygenase-1 (HO-1) and nuclear factor E2-related factor 2 (Nrf2) during LPS/D-GalN-induced liver injury." (PMID 32581788, 2020). "Moreover, EA treatment at ST36 and BL13 attenuates lung injury in rats with endotoxic shock-induced acute lung injury through the activation of NF-E2-related factor pathway and the up-regulation of heme oxygenase-1 expression." (PMID 28810910, 2017). "For example, in potassium chloride-induced hyperuricemic mice, arsenic-exposed mice, and sodium fluoride-induced renal injury rat models, betaine exerts protective effects by regulating urate transporters, inhibiting oxidative stress, and modulating the Nrf-2/heme oxygenase-1 (HO-1) signaling axis." (PMID 41608511, 2026).